EGFR (epidermal growth factor receptor)
Diseases named in the same sentence as EGFR in open-access papers (continued):
Sharing a sentence is not in itself a finding about the gene and the disease.
tumor (continued). "To investigate whether hyperactivated EGFR signaling hampered cell death by cisplatin in the cisplatin-resistant tumor cells, we first performed Western blot analysis of lysates derived from CaSki P and CaSki CR cells." (PMID 37165076, 2023). "Drug resistance in tumor cells is increased by EGFR overexpression." (PMID 37584258, 2023). "Moreover, miR-218-5p served as a tumor suppressor and directly targeted EGFR, which was required for miR-218-5p to suppress cell proliferation, colony formation, migration, angiogenesis, and tumor growth." (PMID 36831545, 2023). "Hence, CD27xEGFR is designed to re-activate anti-tumor immunity safely and effectively in EGFR+ cancer cells." (PMID 37545491, 2023). "This was evident in a clinical trial where the combination of everolimus and the epidermal growth factor receptor (EGFR) inhibitor gefitinib showed limited effectiveness in reducing tumour activity in patients diagnosed with metastatic castration-resistant prostate cancer." (PMID 37513916, 2023). "Bioinformatics analysis revealed gut microbiota may influence ICC development through regulating pathways like AMPK, mTOR, EGFR and tumor immune microenvironment." (PMID 38033576, 2023). "Therefore, eccDNA significantly contributes to the promotion of GSC self-renewal, augmentation of tumor cell stemness, and influencing therapeutic efficacy through EGFR up-regulation." (PMID 39534571, 2023). "Moreover, they change the immunosuppressive environment and thus effectively deliver and extensively accumulate EGFR-TKIs in tumor site, reducing the accumulation of drugs in normal tissues." (PMID 37754880, 2023). "In the context of tumor evolution under therapy, EGFR is prone to experience clonal replacement." (PMID 37537946, 2023). "EGFR affects proliferation, angiogenesis, tumor invasion, metastasis, and apoptosis." (PMID 37035133, 2023). "With down-regulation of CNTN3, EGFR may be abnormally activated and initiate ErbB signaling to promote tumor growth and invasion." (PMID 37978561, 2023). "To confirm whether 18β‐GA enhanced anti‐HCC efficacy of RT is associated with the inactivation of EGFR/ERK/NF‐κB signalling, we performed IHC staining on tumour samples." (PMID 37177859, 2023). "The results showed that genetic mutations in EGFR, KRAS, and BRAF could be successfully detected in the collected tumor cells even when there was only one tumor cell (sample numbers 4 and 15)." (PMID 37849806, 2023). "Clinical trials (e.g., CHRYSALIS; NCT02609776; and others) have shown acceptable toxicity and anti-tumor efficacy of Amivantamab in patients with locally advanced or metastatic NSCLC and EGFR Ex20ins mutations based on the ORR of about 40% and duration of response." (PMID 36900399, 2023). "The primary objectives of the Phase 2 portion of the study are to evaluate the safety and anti-tumor effects of the combination of rociletinib and MPDL3280A, at the best doses for the combination determined in Phase I, in patients with EGFR mutation-positive NSCLC." (PMID 36910653, 2023). "Therefore, in the absence of FR-α, BiTEs released by oncolytic adenovirus (OAd)-infected cells redirected CAR T-cells toward EGFR, addressing tumor heterogeneity." (PMID 37020537, 2023). "Comparable ability of GS‐0189 combined with cetuximab to potentiate phagocytosis by PBMC‐derived macrophages from SIRPαV1/V1‐ and SIRPαV2/V2‐expressing donors was previously demonstrated using HT‐29 cells, the epidermal growth factor receptor–expressing human tumor cell line, as the target cell." (PMID 37206279, 2023). "This differing expression of EGFR in different tumour histologies may indicate different impacts on carcinogenesis in different cancer types." (PMID 38414930, 2023). "Tyrosine kinase inhibitors (EGFR-TKIs) inhibit EGFR and alter the tumor immune microenvironment." (PMID 36941614, 2023).
tumor (continued). "In addition to EGFR, several receptor proteins including GPCRs are also well expressed or often overexpressed in various types of tumours and serve as a potential therapeutic approach." (PMID 38203605, 2023). "Additionally, the combination of disulfiram, an ALDH inhibitor, with erlotinib, an EGFR inhibitor, significantly delayed tumor regrowth in lung cancer xenografts." (PMID 37779896, 2023). "The EGFR pathway promotes cell proliferation and metastasis and drives tumor recurrence." (PMID 37947601, 2023). "Adjuvant atezolizumab or pembrolizumab are not recommended in patients with tumours containing EGFR mutations or ALK translocations based on lack of efficacy in the advanced disease setting." (PMID 37999109, 2023). "Specifically, our findings support a model in which YAP:TEAD-mediated transcription activates an AXL- and EGFR-initiated signaling cascade resulting in the activation of mTOR in epithelial cells, thus representing an actionable target to prevent tumor initiation." (PMID 37961717, 2023). "Additionally, immunohistochemical analysis revealed a significant inhibition of EGFR protein expression in tumor tissues following polyphyllin VII treatment." (PMID 37928267, 2023). "However, the efficacy of first-generation EGFR-TKIs for treating NSCLC-BM is limited by blood-brain barrier (BBB) penetration and exon 20 (T790M) tumor mutations." (PMID 37190312, 2023). "This work reveals a mechanism for the regulation of EGFR conformation and ligand binding within specific subpopulations of EGFR, which has important impact on the understanding EGFR regulation of cell physiology, as well as the role of EGFR as a driver of tumor progression." (PMID 37160944, 2023). "Tumor heterogeneity is higher in patients with the L858R than those with EGFR 19Del, which may explain the difference in PFS between these two subtypes." (PMID 37723846, 2023). "Our results suggest that Kremen2 may prevent the EGFR degradation and play an important role in tumor progression and metastasis of NSCLC." (PMID 37270563, 2023). "In addition, it reduced IL-1β, IL-4, IL-6, IL-10, and IL-13 levels, down-regulated PI3K, ERK1/2, and up-regulated EGFR levels, improving the anti-tumor effects of the tumor suppressor microenvironment." (PMID 37397393, 2023). "It has been shown that Gefitinib could inhibit the catalytic activity of epidermal growth factor receptor (EGFR), inhibiting tyrosine kinase-dependent tumor growth, cell cycle arrest, and angiogenesis." (PMID 37737707, 2023). "Importantly, the presence of EGFR mutations predicts response to specific tyrosine kinase inhibitors (TKIs), likely due to addiction of the respective tumor cells to an active EGFR pathway." (PMID 37894376, 2023). "Other possible reasons for the selective replication of ORFV in cancer cells may be impairments in apoptotic pathways, defects in the cell IFN pathway, and excessive activation of epidermal growth factor receptor/Ras signaling in tumor cells." (PMID 36641456, 2023). "Patients treated with ACT were more likely to be younger, smokers, after sublobectomy, without EGFR mutations, with a micropapillary/solid predominant pattern, larger tumor size, STAS, VPI, and LVI." (PMID 38144332, 2023). "Noteworthy, PDO-33.3 displayed the lowest sensitivity to Lapatinib as single agent (IC50 = 1.3μM), suggesting that concomitant CDK12/13 inhibition may overcome an intrinsic resistance of this specific tumor to EGFR inhibition." (PMID 37202753, 2023). "The anticancer potency of kaempferol was further confirmed in a mice xenograft model, revealing the ability to significantly prevent the growth of tumor size coupled with a marked decrease in hexokinase-2 expression and epidermal growth factor receptor (EGFR) activity in tumor tissues." (PMID 37216013, 2023).
tumor (continued). "It is possible to diagnose cancer cells by tumor receptor detection(epidermal growth factor receptor, proepithelin), malfunction detection, location of tumor cells besides intercellular chemical analysis, and finding targeted cells with dendrimer, NT, nanoshells, iron oxide (FeO) NP and QD." (PMID 36580403, 2023). "EGFR-mutated tumors present their most recent common ancestor (MRCA), a cell containing all the alterations that will lead to carcinogenesis, around the age of 61, which is a median of eight years before the tumor becomes clinically evident." (PMID 37653450, 2023). "However, as a limitation, we observed mutation-calling failure in a few EGFR-TKI treatment cases (11%), which was attributed multiple factors such as biopsy differences, tumor clonality, purity, and sequencing depth." (PMID 36717865, 2023). "We speculate that these tumor types may be composed of heterogenic (but dominantly EGFR- or ALK-mutant) cancer cells that are prone to significant treatment response with targeted therapies." (PMID 37768380, 2023). "Among the downregulated genes were DUSP6 (Dual Specificity Phosphatase 6), a key negative regulator of ERK, and ERRFI1 (ERBB Receptor Feedback Inhibitor 1, also called Mig-6), a tumor suppressor that curbs activation of EGFR and sustained signaling through the ERK pathway." (PMID 37020037, 2023). "Blocking EGFR activity with an EGFR inhibitor can attenuate corticotroph tumor cell proliferation." (PMID 38027207, 2023). "Therefore, EGFR is the most well-studied tyrosine kinase receptor whose signaling is involved in neoplasia." (PMID 37266143, 2023). "This is especially important when attempting to identify tumor in the surgical margins where cell density, and therefore EGFR concentrations, may be low." (PMID 34651290, 2023). "Three patients (D070, D453, and D076) with plasma EGFR mutations carried no identical mutations in the corresponding tumor tissue samples." (PMID 37372399, 2023). "Upon 5-FU and cisplatin treatment, ELF3-mediated transcription and secretion of SPINK1 increase, and potentiate HCC cells’ ability to promote tumor initiation, stemness, dedifferentiation and chemoresistance, by binding to EGFR and consequently driving the ERK-CDK4/6-E2F2 signaling cascade." (PMID 38030644, 2023). "PD-1 inhibitors play an important role in the treatment of patients with mNSCLC and, alongside their development, predictive biomarker testing for tumour genomic aberrations in such genes as EGFR or ALK, and PD-L1 expression have become mandatory in most European countries." (PMID 37386452, 2023). "Crucially, as a consequence of this EGFR feedback model, combining oncogenic RAS inhibitors with clinically used EGFR inhibitors could lead to increased tumor regression and extended survival in patients with KRAS-mutant CRC." (PMID 37020035, 2023). "For example, in the VOLFI trial included in present study, some patients who were initially assigned to cohort 1 (where tumor resection was considered impossible) still achieved resection after receiving anti-EGFR targeted agents in combination with chemotherapy." (PMID 37880688, 2023). "This is an important finding, given that the anti-EGFR therapeutic antibodies cetuximab and panitumumab are contraindicated for RAS-mutated CRCs and may even boost tumor progression in this category of patients." (PMID 36902296, 2023). "With multiple EGFR and MET inhibitors available, trials have studied different combinations of these inhibitors to identify a dual-inhibition strategy with significant anti-tumor activity as well as an acceptable risk profile." (PMID 37296959, 2023). "Recent studies have indicated a correlation between CT texture features tumours characteristics that reflect tumour grade, cellular processes (e.g. hypoxia or angiogenesis) and genetic markers such as KRAS or epidermal growth factor receptor (EGFR) mutation status." (PMID 36620843, 2023).
tumor (continued). "Interestingly, the analysis of the correlation between mRNA levels and the CN status also revealed that the cancer samples with amplified EGFR show a statistically significant increase of CBX3 mRNA expression regardless the tumor tissue of origin." (PMID 37633946, 2023). "Furthermore, YBX1 phosphorylation at Ser102 by the PI3K signalling was recently shown to positively correlate with the expression of EGFR to facilitate cell proliferation and tumour growth." (PMID 36949044, 2023). "Notably, EGFR inhibition has been tested in clinical studies and evaluated to enhance the efficacy of anti-cancer drugs by normalizing the tumor vasculature." (PMID 37175811, 2023). "Moreover, in the 27 tumor samples with high EGFR staining, 28 showed medium, and 18 showed low EGFR staining." (PMID 37542131, 2023). "In addition, RUNX1 has been reported to mediate tumor function by transcriptionally regulating EGFR expression, activating downstream STAT3." (PMID 38057816, 2023). "In addition, our study also showed that the KRAS mutation-positive group had the largest tumor size (2.83 ± 6.87 cm3) relative to ALK (1.23 ± 3.38 cm3) and EGFR (0.51 ± 2.68 cm3) mutation groups." (PMID 37508989, 2023). "Our data indicate that despite the reliable efficacy of VRB, it might have possible unexplored interactions with EGFR and MAPK-associated lncRNAs that could increase the likelihood of tumor proliferation and metastasis." (PMID 38137519, 2023). "In all cases, the presence of EGFR was confirmed both within the primary tumor and its BM." (PMID 37240478, 2023). "We found that tumor cells in the cervical metastatic lymph nodes also had high EGFR expression." (PMID 36814816, 2023). "Through a complex mechanism which involves a DNA damage signaling pathway, interferon γ (IFNγ) signaling, the cyclic GMP–AMP synthase–stimulator of interferon genes (cGas–STING) pathway, and the epidermal growth factor receptor (EGFR) pathway, the PD-L1 receptor of the tumor cells is upregulated." (PMID 37894347, 2023). "This is the first prospective study to demonstrate the ability of follow‐on ctDNA testing to detect informative genomic alterations in patients with advanced NSCLC for whom initial tumor tissue testing was negative for at least EGFR mutations." (PMID 37948122, 2023). "However, the epidermal growth factor receptor (Egfr), enhancing inflammatory cytokine signaling, thereby promoting tumor cell progression, was down-regulated (r = −0.3316, p = .02132) by the increase in CR." (PMID 36757838, 2023). "EGF can promote the activation of EGFR, thereby promoting the rapid proliferation of tumor cells." (PMID 36674593, 2023). "In addition, patients with EGFR mutations have a relatively low response rate to PD-1/PD-L1 inhibitors, and the combined expression rate of PD-L1 and CD8+ of tumor-infiltrating lymphocytes is low." (PMID 36910653, 2023). "Nine variants reported in the tumor tissue across EGFR, KRAS, BRAF, and PIK3CA were not covered by the UltraSEEK® Lung Panel." (PMID 37686200, 2023). "(ii) Receptor tyrosine kinases (RTK): The activation of RTKs, such as EGFR, ERBB2, KIT, and PDGFR, by mutation or translocation directly leads to tumor growth and is a clear therapeutic target; these mutations were detected in 216 of 1003 cases or around 20% of the cases." (PMID 36251535, 2023). "EGFR influences tumor growth and the neoplastic transformation." (PMID 37936777, 2023). "Most targeted therapeutics for GBM account for 1 to 2 targets in the GBM tumor, such as epidermal growth factor receptor (EGFR) and isocitrate dehydrogenase (IDH1), allowing cancer cells without expressing specific targets to survive and eventually kill the patient." (PMID 37100462, 2023). "In the CCA group, however, EGFR was strongly related to high tumour size (p = 0.047)." (PMID 38414954, 2023).
tumor (continued). "Because of the tumor heterogeneity, different treatments have different sensitivities to various tumor cells, that’s why we need combination therapy to cover more cell subsets or overcome the acquired EGFR-TKIs resistance." (PMID 37316870, 2023). "Some evidences have shown that signaling pathway that steer resistance to therapeutic treatment can intersect with the signaling of cell invasion, but the shared mechanisms still need to be fully discovered including in EGFR-TKIs resistance-induced tumor progression." (PMID 37919290, 2023). "Therefore, the identification of tumours bearing EGFR ex20ins is important in guiding treatment decisions, and universal molecular testing should be able to accurately and comprehensively detect the wide range of variants that have been identified thus far." (PMID 36269676, 2023). "EGFR exon-19 deletion was considered clonal event at the trunk of tumor development." (PMID 37634047, 2023). "Dr. Rosenthal’s clinical studies have suggested that the anti-EGFR-labeled tracers may drain from the tumor to sentinel lymph nodes (SLN) by indirect or passive drainage from the primary tumor (just as if it were directly injected)." (PMID 37193364, 2023). "Furthermore, they found significantly decreased EGFR mRNA in tumor tissue after retro-orbital injection of solid lipid NPs loaded with EGFR siRNA at 8, 9, and 11 days post-GL261 tumor implantation in mice." (PMID 35890738, 2022). "The insufficient concentration of TKIs in cerebrospinal fluid (CSF), which is less likely to permanently control the dissemination of tumor cells, is crucial in BM after resistance to prior generation EGFR TKIs, apart from the mechanism-induced acquired resistance." (PMID 35785185, 2022). "The reasons for such an unexpected finding was likely that, while EGFR may be highly expressed in the original tumour, it is strongly downregulated (more than 1,000 times) in metastases by a yet unknown mechanism." (PMID 36380366, 2022). "The significant difference in tumor status between the GA + AA and GG genotypes with EGFR wild-type status was also observed when all patients were analyzed, as 43.7% of those with the GA + AA genotype had advanced (T3/T4) tumors compared with 28.2% with the GG genotype (p = 0.021)." (PMID 36429891, 2022). "Moreover, LY3164530 and JNJ-61186372 bispecific antibodies bind to c-Met and EGFR and have shown good results in inhibiting tumor growth." (PMID 35986321, 2022). "Only an EGFR T790M mutation was detected without C-MET amplification or EMT in the resistant tumor tissue." (PMID 35326664, 2022). "Briefly, a depletion of CD45(+) leukocytes was carried out by adding an anti-CD45 antibody to exclude nonspecific labeling of the probe in infiltrating immune cells, followed by the addition of HX103 and EGFR antibody to obtain the percent of HX103 labeling in EGFR-positive tumor cells." (PMID 36376325, 2022). "In addition, alterations of EGFR itself (polymorphisms, variants), overexpression of HER family ligands, and lncRNAs are associated with monoclonal antibody resistance and tumor relapse." (PMID 35563171, 2022). "The other cluster with lower stage and more differentiated tumor grade, no distant metastasis, and negative EGFR expression represent patients at low risk of death (alive patients)." (PMID 36188649, 2022). "To define the underpinnings of the distribution of EGFR+ tumor cells into five transcriptionally distinct clusters, we determined the number and area of EGFR+ cells and showed a progression from multiple EGFR+ single-cell to small independent clusters to a single observable mass over time." (PMID 35624211, 2022). "We found two EGFR, two PI3Kp110β, and, mostly, two dual inhibitors with anti-tumor effects." (PMID 35884571, 2022).